KHDRBS2 (KH RNA binding domain containing, signal transduction associated 2)
Description:
RNA-binding protein that plays a role in the regulation of alternative splicing and influences mRNA splice site selection and exon inclusion. Binds both poly(A) and poly(U) homopolymers. Phosphorylation by PTK6 inhibits its RNA-binding ability (By similarity). Induces an increased concentration-dependent incorporation of exon in CD44 pre-mRNA by direct binding to purine-rich exonic enhancer. Can regulate alternative splicing of NRXN1 in the laminin G-like domain 6 containing the evolutionary conserved neurexin alternative spliced segment 4 (AS4) involved in neurexin selective targeting to postsynaptic partners. Regulates cell-type specific alternative splicing of NRXN1 at AS4 and acts synergystically with SAM68 in exon skipping. In contrast acts antagonistically with SAM68 in NRXN3 exon skipping at AS4. Its phosphorylation by FYN inhibits its ability to regulate splice site selection. May function as an adapter protein for Src kinases during mitosis.
Synonyms: SLM-1; SLM1; MGC26664; KHDRBS2-OT; KHDRBS2-OT1
Tractability: PROTAC: ubiquitination databases record sites on it; its protein half-life has been measured.
Gene: Protein-coding gene on chromosome 6 (61,630,234 to 62,286,225, reverse strand). Ensembl gene ENSG00000112232.
Subcellular location: Nucleus
Pathways (Reactome):
Signal Transduction: PTK6 Regulates Proteins Involved in RNA Processing
Gene Ontology:
Molecular function: protein binding; poly(A) binding; nucleic acid binding; poly(U) RNA binding; RNA binding; SH2 domain binding; SH3 domain binding
Biological process: regulation of alternative mRNA splicing, via spliceosome; regulation of mRNA splicing, via spliceosome
Cellular component: nucleoplasm; nucleus
Genetic constraint (gnomAD): Loss-of-function variants: 9 observed, 17.76 expected, observed/expected ratio (o/e) 0.51, 90% interval 0.31 to 0.88. The synonymous counts are far from expectation, so gnomAD's model fits this gene poorly and the ratio says little. Missense variants: 244 observed, 234.12 expected, observed/expected ratio (o/e) 1.04, 90% interval 0.94 to 1.16. Synonymous variants: 107 observed, 82.01 expected, observed/expected ratio (o/e) 1.3, 90% interval 1.12 to 1.53.
Homologues: Orthologues: chimpanzee KHDRBS2 (100% identical), macaque KHDRBS2 (99% identical), dog KHDRBS2 (98% identical), pig KHDRBS2 (98% identical), rabbit KHDRBS2 (97% identical), mouse Khdrbs2 (95% identical), rat Khdrbs2 (95% identical), guinea pig KHDRBS2 (87% identical), tropical clawed frog khdrbs2 (78% identical), zebrafish khdrbs2 (73% identical), Drosophila melanogaster qkr54B (35% identical), Drosophila melanogaster qkr58E-1 (34% identical), and 6 more. Paralogues in human: KHDRBS3 (68% identical), KHDRBS1 (63% identical), QKI (34% identical), SF1 (28% identical).
Diseases named in the same sentence as KHDRBS2 in open-access papers:
KHDRBS2 is named in the same sentence as 31 diseases in open-access papers, as found by Europe PMC text mining. Sharing a sentence is not in itself a finding about the gene and the disease. The quoted sentences say what the papers report.
lung adenocarcinoma (4 papers, 2010 to 2023). A carcinoma that arises from the lung and is characterized by the presence of malignant glandular epithelial cells. "Nomogram analysis was also used in this study, and the results also showed that SMAD9, KHDRBS2, and RBM10 had a certain risk correlation with the survival rate of lung adenocarcinoma patients." (PMID 37509501, 2023). "As for KHDRBS2, although the relation of KHDRBS2 overexpression to better OS in lung adenocarcinoma is well understood, little is known about it in GBM." (PMID 34733320, 2021). "We performed high-resolution array comparative genomic hybridization analysis of lung adenocarcinoma in sixty never smokers and identified fourteen new minimal common regions (MCR) of gain or loss, of which five contained a single gene (MOCS2, NSUN3, KHDRBS2, SNTG1 and ST18)." (PMID 21151896, 2010).
Alzheimer disease (3 papers, 2015 to 2023). A progressive, neurodegenerative disease characterized by loss of function and death of nerve cells in several areas of the brain leading to loss of cognitive function such as memory and language. "The variant rs7989332 in CRYL1 was found to interact with rs6455128 in KHDRBS2 (KH domain containing, RNA binding, signal transduction associated 2) and be protective against Alzheimer’s Disease." (PMID 36607984, 2023).
glioma (3 papers, 2017 to 2021). A benign or malignant brain and spinal cord tumor that arises from glial cells (astrocytes, oligodendrocytes, ependymal cells). "In GBM, KHDRBS2 is significantly downregulated in two glioma cells lines LN229 and U373 cell lines and can be re-upregulated with different concentration of 5-aza-2-deoxycytidine, methylation inhibitor." (PMID 31032367, 2019). "We also validated the expression pattern of two upregulated (METTL1 and OAS1) and three downregulated genes (KHDRBS2, RANBP17 and ELAVL3) in glioma cell lines using qRT-PCR." (PMID 28035070, 2017). "Collectively, these results conclude that downregulation of KHDRBS2, RANBP17 and ELAVL3 in glioma is indeed due to DNA methylation." (PMID 28035070, 2017).
lung carcinoma (2 papers, 2020 to 2023). "Abundant studies declared that KHDRBS2 was a prognostic marker of lung cancer, and large-scale population GWAS showed that KHDRBS2 was associated with lung airflow (the FEV/FEC ratio)." (PMID 37055782, 2023).
renal cell carcinoma (2 papers, 2019 to 2021). "Moreover, in renal cell carcinoma, KHDRBS2 is reported to form fusion part with TFEB, which is associated with the aggressive behavior of renal cell carcinoma." (PMID 31032367, 2019).
atrial septal defect (1 paper, 2023). Interauricular communication is a congenital malformation characterized by a communication between the atrial chambers of the heart. "Large-population GWAS studies showed that KHDRBS2 was associated with lung function (FEV/FEC ratio) and atrial septal defects." (PMID 37055782, 2023). "KHDRBS2 is an important member of PTK6 signaling and is associated with atrial septal defect." (PMID 37055782, 2023).
hepatocellular carcinoma (1 paper, 2019). A malignant tumor that arises from hepatocytes. "KHDRBS2 is muted in hepatitis B virus-induced hepatocellular carcinoma and closely related to the prognosis of HBV-induced hepatocellular carcinoma." (PMID 31032367, 2019).
metastatic cancers (1 paper, 2021). A carcinoma which has spread from the original site of growth to another anatomic site. "We also identified six genes (KHDRBS2, IQSEC1, ARHGEF1, ARID5A, IRX5, and TMC6) that were activated in metastatic cancers in two of the three cancer types and might be associated with metastatic traits." (PMID 34294701, 2021).
mullerian aplasia (1 paper, 2019). "Efforts to identify causative genes within regions of copy number variation in patients affected with Mullerian aplasia have turned up candidate genes such as KHDRBS2, and GFRA1, which we see uniquely expressed in the ‘inhibited progenitor’ cluster." (PMID 31232694, 2019).
cancer (11 papers, 2010 to 2025). A tumor composed of atypical neoplastic, often pleomorphic cells that invade other tissues. "In three cases, recurrent cancer-associated missense mutations in RBPs increased binding to RNA: KHDRBS2, A1CF, and PCBP1." (PMID 33692367, 2021). "KHDRBS2 has a regulatory role in microenvironmental permeability, hereditary retinopathy, and cancer." (PMID 36721228, 2023). "We apply easyCLIP to the 33 most recurrent cancer mutations across 28 RBPs, finding increased RNA binding per RBP molecule for KHDRBS2 R168C, A1CF E34K and PCBP1 L100P/Q cancer mutations." (PMID 33692367, 2021). "To further explore the impacts of mutant RBPs in cancer, we analyzed the transcriptomic effects of recurrent missense mutations in PCBP1 and KHDRBS2." (PMID 33692367, 2021). "Somatic mutations in genes within narrow MCR, including FLT4, MAPK9, SPO11 and KHDRBS2, have been reported in cancers (COSMIC v48 release)." (PMID 21151896, 2010). "Of those, eight (HOXA3, HOXA5, ATP10A, SOX2, MIR922, ADAMTSL1, KHDRBS2, and LITD1) were hypermethylated in at least one LS tumor group like here in FAP normal, whereas NEDD4L, and FOXP1 were hypermethylated in LS carcinomas and here in LS normal." (PMID 40753397, 2025). "The expression of KHDRBS2 and MYOZ1 was downregulated in the LUAD cancer samples compared with that in the para-tumor normal samples, whereas the expression of BARX1, ENTPD2, and GFRA3 was upregulated in LUAD cancer tissues." (PMID 36353226, 2022). "According to the data, numerous genes (such as H2AFX, CDKN2A, TTF2, IKBKE, and UBE2I) were markedly upregulated in many cancer types, while some genes (such as ARRB1, LMO3, KHDRBS2, CIRBP, and RALYL) were remarkably downregulated in multiple cancer types." (PMID 35003212, 2021).
tumor (6 papers, 2020 to 2025). "The MeRIP-qPCR and WB results showed that although the m6A methylation levels of KHDRBS2 and RFXAP were both increased in tumor tissues, the protein expression levels of KHDRBS2 was decreased, while RFXAP protein expression was unchanged." (PMID 34422827, 2021). "Downregulated KHDRBS2 displayed a positive correlation with survival, so it might function as a tumor suppressor gene in GBM." (PMID 34733320, 2021). "We also compared the expression level of these SFs in GBM tumor tissues and adjacent normal tissues and found that 7 factors were significantly dysregulated, including HNRNPA1, HNRNPC, HNRPLL, NOVA1, SF3B1, KHDRBS2, and TIA1." (PMID 34326872, 2021). "Specifically, the expression of KHDRBS2 and MYOZ1 was downregulated in LUAD tumor samples." (PMID 36353226, 2022). "We further verified the expressions of RFXAP and KHDRBS2 mRNAs in 19 LUAD patients, the results showed that RFXAP and KHDRBS2 expressions in tumor tissues were lower than that in matched normal adjacent lung tissues, which were consistent with that of GEPIA database." (PMID 34422827, 2021).
KHDRBS2 also shares sentences with these, for which no sentence is quoted: ankylosing spondylitis (1 paper); autoimmune disease (1); Barrett's oesophagus (1); brain tumors (1); cardiovascular diseases (1); colorectal cancer (1); coronary artery disease (1); diabetes (1); glioblastoma (1); Huntington disease (1); infection (1); Lewis body disease (1); major depressive disorder (1); male infertility (1); Obesity (1); oesophageal adenocarcinoma (1); papillary thyroid carcinoma (1); Parkinson disease (1); psoriasis (1); rheumatoid arthritis (1).